DSG1 (desmoglein 1)
Diseases named in the same sentence as DSG1 in open-access papers (continued):
Sharing a sentence is not in itself a finding about the gene and the disease.
pemphigus foliaceus (continued). "In pemphigus foliaceus, the antigenic target is desmoglein 1 (Dsg1), which is expressed at high concentrations in the superficial layers of the epidermis; in pemphigus vulgaris, the mucosal-dominant type antibodies target desmoglein 3 (Dsg3) in basal and parabasal layers of the skin." (PMID 29483905, 2018). "In the pemphigus foliaceus (PF) subgroup, only antibodies against Dsg1 are present, whereas in pemphigus vulgaris (PV) antibodies against Dsg3 are found in mucosal dominant PV (mdPV), or together with anti-Dsg1 in mucocutaneous PV (mcPV)." (PMID 29740444, 2018). "The target antigen in pemphigus foliaceus is desmoglein-1, a 160 kDa constituent of desmosomes." (PMID 24416609, 2013). "In HaCat cells, desmoglein-1 underwent internalization in response to sera collected from pemphigus vulgaris and pemphigus foliaceus patients as early as 6 hours with a concurrent decrease in the amount of desmoglein-1 found in the membrane-associated fraction postexposure." (PMID 22312325, 2012). "Pemphigus foliaceus (PF) is an autoimmune blistering disease characterized by the disruption of the epidermal cell adhesion protein desmoglein 1 (DsG1)." (PMID 39734965, 2024). "Pemphigus foliaceus (PF) describes patients whose blistering is limited to cutaneous sites, who generate antibodies against DSG1 alone, in all but a handful of cases." (PMID 38074463, 2023). "Clinically, the initial severity of pemphigus foliaceus (PF) and PV is correlated with anti-DSG1 and anti-DSG3 Ab serum levels, respectively." (PMID 35371083, 2022). "For example, multiplexed barcoded antigen proteins DSG1 and 3, which are functionally compensatory, could be utilized for a quantitative and sensitive detection to distinguish two autoantibodies related to PV and pemphigus foliaceus." (PMID 31752022, 2020). "In pemphigus foliaceus (PF), nearly all antibodies target Dsg1 leading to subcorneal blistering in the skin only." (PMID 33297481, 2020). "Pemphigus vulgaris (PV) usually is associated with autoantibodies against Dsg3 whereas pemphigus foliaceus (PF) patients present autoantibodies against Dsg1." (PMID 31178865, 2019). "Anti-DSG3 antibodies (Abs) are observed in pemphigus vulgaris (PV) with mucosal involvement, and anti-DSG1 Abs are observed in patients with pemphigus foliaceus (PF) and those with PV and skin involvement." (PMID 31440235, 2019). "DSG3 provide desmogleing compensations with DSG1 in pemphigus foliaceus (PF), which is a potentially fatal autoimmune blistering skin disease in which autoantibodies against DSG3 and DSG1 cause loss of keratinocyte cell adhesion." (PMID 30510564, 2018). "Dsg1 is being targeted and DIF revealed IgG and C3 deposition in a granular pattern at the intercellular junction confirming the diagnosis of pemphigus foliaceus." (PMID 39100801, 2024). "It is now known that pemphigus foliaceus (PF) is characterized by autoantibodies to desmoglein (Dsg) 1 and pemphigus vulgaris (PV) is characterized by autoantibodies to Dsg3, although 60% of PV sera also contain Dsg1 autoantibodies." (PMID 36013115, 2022). "Pemphigus foliaceus (PF) is an autoimmune, blistering skin disease, targeting desmoglein-1." (PMID 24416609, 2013). "Pemphigus foliaceus (PF) and staphylococcal scalded skin syndrome (SSSS) are subcorneal blistering diseases resulting from loss of function of the desmosomal cadherin, desmoglein 1 (Dsg1)." (PMID 20631906, 2010). "In contrary, expression of antibodies against desmoglein 1 and desmoglein 3 is characteristic rather of pemphigus vulgaris (PV), pemphigus foliaceus (PF) and paraneoplastic pemphigus (PNP) but not PAMS." (PMID 33995340, 2021). "Pemphigus foliaceus (PF) is an autoimmune blistering disease characterized by superficial blisters due to the autoantibody-mediated disruption of the epidermal cell adhesion protein desmoglein 1 (DsG1) and not desmoglein 3 (DsG3)." (PMID 39734965, 2024).
pemphigus vulgaris (54 papers, 2009 to 2026). Pemphigus is a group of chronic autoimmune skin diseases characterized by blister formations on the outer layer of the skin and the mucous membranes. "Pemphigus vulgaris (PV) is a rare blistering skin disease caused by autoantibodies against desmoglein 1 and 3 (DSG1/3)." (PMID 40873568, 2025). "Background and Objectives: Pemphigus vulgaris (PV) is a rare autoimmune blistering disease caused by IgG au-toantibodies against desmoglein 1 and/or desmoglein 3, leading to flaccid blisters on the skin and mucous membranes." (PMID 41597317, 2025). "In the bullous autoimmune disease pemphigus vulgaris (PV), autoantibodies directed mainly against desmoglein 1 (Dsg1) and Dsg3 cause loss of desmosomal adhesion." (PMID 40299565, 2025). "Anti-Dsg1 IgG4 is responsible for the development of pemphigus foliaceous (PF), while anti-Dsg3 IgG4 antibodies, and in some cases anti-Dsg1 IgG4, cause pemphigus vulgaris." (PMID 38433835, 2024). "Pemphigus vulgaris (PV) is a potentially lethal autoimmune bullous skin disorder caused by IgG autoantibodies against desmoglein 3 (Dsg3) and Dsg1." (PMID 37174740, 2023). "Apart from that, in another desmosomal disease, pemphigus vulgaris (PV), an autoimmune condition caused by autoantibodies against DSG1 and/or DSG3, which leads to blister formation in skin and mucosa, p38MAPK is activated, which can be recapitulated in vitro." (PMID 36733457, 2023). "The severe autoimmune blistering disease Pemphigus vulgaris (PV) is mainly caused by autoantibodies (IgG) against desmoglein (Dsg) 3 and Dsg1." (PMID 35844545, 2022). "Pemphigus vulgaris (PV) is an autoimmune disease in which circulating autoantibodies (PV-IgG) targeting Dsg1 and/or 3 cause skin blistering and erosions of the epithelial lining of the oral cavity." (PMID 31867019, 2019). "Pemphigus vulgaris (PV) is an autoimmune disease in which circulating autoantibodies (PV-IgG) targeting Dsg1 and 3 cause characteristic epidermal blister formation." (PMID 31867019, 2019). "Pemphigus vulgaris (PV) shows the production of anti-Dsg3 in the mucosal form, and anti-Dsg1 and 3 in the mucocutaneous form." (PMID 38851894, 2024). "In general, AIBDs are typically described as targeting a single antigen, with autoantibodies to secondary antigens acquired via epitope spreading, i.e., desmoglein 1 (Dsg1) in mucocutaneous-type pemphigus vulgaris (PV) or BP230 in BP." (PMID 39584991, 2024). "The mucocutaneous pemphigus vulgaris (PV) presents in both mucosal epithelia and the epidermis and is characterized by IgG autoantibodies (auto-abs) directed against desmoglein 1 (Dsg1) and Dsg3 antigens, which were identified over three decades ago." (PMID 37180099, 2023). "In this paper, we reviewed the literature about the detection of autoantibodies against desmoglein 1 and 3, the main target antigens of pemphigus vulgaris, in patient with OLP, summarizing the more recent insights on this topic." (PMID 36263026, 2022). "Pemphigus vulgaris (PV) is a rare autoimmune blistering disease characterized by the development of autoantibodies targeting desmoglein (Dsg) 3, but also against Dsg1 in mucocutaneous disease." (PMID 34731225, 2021). "Serologically, the predominantly cutaneous presentation has circulating anti-Dsg1 and anti-Dsg3 autoantibodies, with a tendency to higher titers of anti-Dsg1 than anti-Dsg3, which implies a rare clinical phenotype of pemphigus vulgaris." (PMID 34006398, 2021). "The aim of this investigation was to evaluate the correlation between serum desmoglein 1 and 3 auto-antibodies and the severity of disease in patients with pemphigus vulgaris." (PMID 32509225, 2020). "Antibody profiles of pemphigus vulgaris patients' IgG fractions as determined by ELISA for Dsg1 or Dsg3, respectively, and clinical phenotype." (PMID 31024527, 2019).
pemphigus vulgaris (continued). "Pemphigus vulgaris (PV) is a blistering autoimmune disease of the epidermis, characterized by IgG autoantibodies mainly against the desmosomal adhesion proteins, especially desmoglein-3 (Dsg3) and desmoglein-1 (Dsg1)." (PMID 39450168, 2024). "Pemphigus vulgaris (PV) is a chronic, potentially lethal autoimmune mucocutaneous bullous disease mediated by essentially IgG autoantibodies directed against desmogleins 1 and 3 (Dsg1 and Dsg3), cadherin-type cell–cell adhesion molecules present in desmosomes." (PMID 37511259, 2023). "These may present the same peptide from Dsg1, while in pemphigus vulgaris, two distinct types of peptide may be presented by DRB1*04:02 or DRB1*14/04:06." (PMID 33584677, 2020). "Pemphigus vulgaris (PV) is a very rare chronic bullous disease (1:1,000,000) which typically occurs in patients aged between 45 and 65 years, and it is characterized by the formation of autoantibodies, mainly of the IgG class, directed against desmoglein-1 and desmoglein-3 (Dsg1 and Dsg3 protein)." (PMID 37371152, 2023). "Furthermore, DRB1*14/04:06 may be able to present both Dsg1 and Dsg3 peptides, which may be the reason for antibodies against both antigens in pemphigus vulgaris with muco-cutaneous clinical phenotype." (PMID 33584677, 2020). "Autoantibodies (autoAbs) against desmoglein-1 (DSG1) and desmoglein-3 (DSG3) have conventionally been studied and well accepted in the pathogenesis of pemphigus vulgaris (PV) and foliaceus (PF)." (PMID 32555697, 2020). "Furthermore, PKP3 binds in vivo to several other primary pemphigus vulgaris autoantigens including DSG3, DSG1, DSC1, and DSC3." (PMID 24988487, 2014). "Pemphigus vulgaris (PV) is the most common subtype of a group of rare autoimmune blistering disorders (AIBD) in which autoantibodies primarily directed against the cell-cell adhesion molecules desmoglein 3 (Dsg3) and desmoglein 1 (Dsg1) lead to characteristic epidermal blistering." (PMID 36703956, 2022). "Finally, antibodies against DSG1 and DSG3 have been identified in pemphigus vulgaris or foliaceus." (PMID 27669234, 2016).
autoimmune disease (21 papers, 2010 to 2025). A disorder resulting from loss of function or tissue destruction of an organ or multiple organs, arising from humoral or cellular immune responses of the individual to their own tissue constituents. "Pemphigus is an autoimmune disease affecting skin and mucous membranes, with pathogenic autoantibodies directed against desmogleins 1 and 3 (Dsg1 and Dsg3)." (PMID 32158442, 2020). "Pemphigus is a severe, potentially life-threatening autoimmune disease associated with mucous and cutaneous blisters caused by autoantibodies against cell adhesion proteins desmogleins 1 (Dsg1) and 3 (Dsg3)." (PMID 26417354, 2015). "Endemic pemphigus foliaceus (PF), also known as fogo selvagem (meaning ‘wild fire'), is an organ-specific autoimmune disease characterized by autoantibodies against desmoglein 1 protein and by loss of adhesion between keratinocytes, leading to intraepithelial blisters of the skin." (PMID 21637411, 2010). "PV is an autoimmune disease with autoantibody development against the desmosomal cadherins DSG1 and DSG3, resulting in blister formation in the skin and oral mucosa." (PMID 41037786, 2025). "Gene set analysis of the 100 most significant genes in the DNAemia meta-analysis found significant enrichment of genes associated with autoimmune disease of skin and connective tissue (DOID:0060039: FDR = 0.02; TG, DSG1,DST, LAMA3, HLA-DRB1)." (PMID 38005904, 2023). "The opposite impact of the IgG4 subclass and Fc-FcγR interaction on the pathogenic function of autoantibodies in anti-ADAMTS13 and anti-Dsg1 autoantibodies suggests that these autoantibodies have different modes of action in IgG4-mediated autoimmune diseases." (PMID 35920621, 2022). "A reduction of Cx43 levels was also observed in areas with reduced Dsg1 in PF patient epidermis, suggesting that our reported dependence of Cx43 stability on Dsg1 holds true across genetic and autoimmune disease." (PMID 34905516, 2022). "PF is an autoimmune disorder in which circulating anti-Dsg1 autoantibodies bind to Dsg1 and interfere with cell-cell adhesion through steric hindrance and/or by stimulating endocytic turnover." (PMID 34905516, 2022). "While our study of anti-ADAMTS13 autoantibodies supports the notion that switching to immune-inert IgG4 subclass is a protective mechanism in IgG4-mediated autoimmune diseases, our analysis of anti-Dsg1 autoantibodies suggests the opposite." (PMID 35920621, 2022). "Pemphigus foliaceus is an organ-specific autoimmune disease characterized by autoantibodies against the extracellular region of desmoglein 1, a protein that mediates intercellular adhesion in desmosomes." (PMID 21637411, 2010). "PV is an autoimmune disease characterized primarily by the presence of IgG antibodies against Dsg1 and Dsg3 due to the involvement of immune responses mediated by B cells (crucial to producing specific autoantibodies) and T cells (participating in the onset and persistence of PV)." (PMID 40649854, 2025). "This has raised the concern the binding of unrelated antibodies to Dsg-proprotein could lead to false positive detection of anti-Dsg3 or 1 antibodies, as has been shown for anti-Dsg1 in healthy controls and patients with the unrelated autoimmune disease thrombotic thrombocytopenic purpura." (PMID 36211362, 2022).
dermatitis (21 papers, 2014 to 2025). An inflammatory process affecting the skin. "Mutations in DSG-1 are linked to dermatitis, multiple allergies, and metabolic wasting, highlighting DSG-1’s essential role in maintaining skin integrity and its involvement in disease." (PMID 40901964, 2025). "Decreased DSG1 activity (secondary to reduced expression or genetic mutation) is highly associated with various human skin disorders." (PMID 39439565, 2024). "Desmoglein‐1 (DSG1) (Gene ID: 1828) is associated with severe dermatitis, multiple allergies and metabolic wasting syndrome." (PMID 33624385, 2021). "As the IL-17/IL-23 skewed gene signature is present before birth in Dsg1-null embryos, genetically induced loss of Dsg1 could predispose individuals to skin inflammation." (PMID 34905516, 2022). "Future work to analyze shared and distinct features of Dsg1 deficiency and common skin disorders could provide an opportunity to develop more targeted therapeutic approaches for both rare and common inflammatory disorders." (PMID 34905516, 2022). "A different set of more severe human skin disorders, but with molecular defects that resemble our ninein-knockout, have been reported from patients with mutations in the genes encoding desmoglein 1 or desmoplakin, leading to desmosomal defects and to dermatitis." (PMID 30923192, 2019). "These toxins cleave a desmosomal protein, desmoglein 1 (Dsg1), crucial for cell–cell adhesion in the epidermis, thus leading to blistering skin disorders." (PMID 36077258, 2022). "Defects in desmoglein 1 (DSG1) or desmoplakin (DSP), structural desmosomal proteins, cause severe dermatitis, multiple allergies, and metabolic wasting (SAM) syndrome, a severe multisystemic disease resembling IPEX syndrome at least clinically." (PMID 32226610, 2020). "PKP1 interacts with desmosomal proteins and regulates desmosomal turnover and signaling, and the interaction between DSG1 and SPINK5 is evidenced by increased DSG1 degradation in mice deficient in SPINK5 as a model of Netherton syndrome, a skin disorder." (PMID 32735560, 2020). "Severe dermatitis, multiple allergies, and metabolic wasting (SAM) syndrome is a recently recognized syndrome caused by mutations in the desmoglein 1 gene (DSG1)." (PMID 26073755, 2015). "Recently, a hereditary disease with a new syndrome featuring severe dermatitis, multiple allergies and metabolic wasting syndrome (SAM syndrome) caused by homozygous mutations in DSG1 has been described." (PMID 25119884, 2014). "In addition, our work raises the possibility that Dsg1 reduction could be a biomarker for Th17 skewing and taken into consideration when designing therapeutic protocols for skin disorders." (PMID 34905516, 2022). "Additionally, Cops3 has been implicated in keratinocyte interleukin signaling, which is interesting in light of the recent observation that loss of Dsg1 leads to an increase in inflammatory mediators in SAM syndrome, featuring severe dermatitis, multiple allergies, and metabolic wasting." (PMID 28891468, 2017). "A large number reports show that the lack of DSG1 will damage the integrity of the skin epithelium, induce cell separation and lead to various dermatitis, multiple allergies, and metabolic wasting." (PMID 29921748, 2018).